EGOT (eosinophil granule ontogeny transcript)
Synonyms: EGO; NCRNA00190
Gene: Long non-coding RNA gene on chromosome 3 (4,749,192 to 4,751,590, reverse strand). Ensembl gene ENSG00000235947.
Diseases named in the same sentence as EGOT in open-access papers:
EGOT is named in the same sentence as 19 diseases in open-access papers, as found by Europe PMC text mining. Sharing a sentence is not in itself a finding about the gene and the disease. The quoted sentences say what the papers report.
breast carcinoma (12 papers, 2016 to 2026). "Studies on EGOT have found that the expression of EGOT is negatively correlated with the survival of breast cancer patients, which is mainly caused by the inactivation of lncRNA EGOT through the Hedgehog pathway." (PMID 39411134, 2024). "According to the coefficient of each lncRNA, we found that HOTAIR and AC115837.2 increased the risk score of a breast cancer patient, while U62317.4, EGOT, MAPT-AS1, and SEMA3B-AS1 tended to decrease the score." (PMID 35990656, 2022). "Lower EGOT expression has been associated with improved survival in rectal, gastric, and colon cancers, while higher expression correlates with poorer outcomes in breast cancer." (PMID 40299341, 2025). "Analyses of clinical breast cancer samples have shown that patients with low EGOT expression have a high level of paclitaxel resistance and that EGOT may be utilized as a diagnostic biomarker of paclitaxel treatment for breast cancer patients after surgery." (PMID 33407694, 2021). "To confirm whether purmorphamine can reverse the expression of genes in the Hh signaling pathway caused by an overexpression in EGOT in breast cancer, we transfected BT549 cells with pcDNA–EGOT or pcDNA." (PMID 32150666, 2020). "Moreover, the results were further validated in TCGA breast cancer patients treated with paclitaxel, which showed that high expression of EGOT was also associated with favorable OS, in accordance with our study." (PMID 30999914, 2019). "As a result, a six-genomic instability-related lncRNA signature (U62317.4, MAPT-AS1, AC115837.2, EGOT, SEMA3B-AS1, and HOTAIR) was identified as the independent prognostic risk model for breast cancer patients." (PMID 35990656, 2022). "EGOT is a unique estrogen-regulated lncRNA, which should be explored in treating ER+ breast cancers, along with other chemotherapeutic agents." (PMID 32466143, 2020). "We observed that EGOT is significantly down‐regulated in breast cancer tissues and cell lines, and EGOT expression is negatively correlated with the Ki67 expression." (PMID 32150666, 2020). "The quantitative real‐time PCR (qRT‐PCR) results exhibited that the relative level of EGOT expression was significantly down‐regulated in breast cancer cell lines BT549, MDA‐MB‐231, MCF7 and SKBr3, compared with control cell lines in HEK293." (PMID 32150666, 2020). "EGOT was greatly down‐regulated in breast cancer tissues and cell lines, and the relative level of EGOT was negatively correlated with the expression of Ki67." (PMID 32150666, 2020). "The expression of EGOT from BT549 was the lowest among these breast cancer cell lines, with BT549 being used for further functional experiments." (PMID 32150666, 2020). "This is consistent with a previous study, which showed that downregulation of EGOT correlates with worse clinicopathological features and poor prognosis in breast cancer." (PMID 32231885, 2020). "To further uncover the role of EGOT in breast cancer, we studied the relationship between EGOT and the Hh signaling pathway." (PMID 32150666, 2020). "High expression of EGOT was associated with favorable OS and RFS) in breast cancer patients, while loss of ITPR1 indicated worse RFS in the HMUCC cohort." (PMID 30999914, 2019). "In our previous study, we first reported that downregulation of EGOT expression was correlated with advanced malignant status and worse prognosis in breast cancer." (PMID 30999914, 2019). "Regarding the function of Ai-lncRNA EGOT, we first reported that low levels of EGOT expression were significantly correlated with increased tumor size, lymph node metastasis, and Ki-67 expression in human breast cancer." (PMID 30999914, 2019). "As expected, overexpression of EGOT increased LC3-II/LC3-I levels and reduced P62 expression in HeLa and breast cancer cells, while knockdown of EGOT reduced LC3-II/LC3-I levels and increased P62 expression." (PMID 30999914, 2019).
breast carcinoma (continued). "More importantly, breast cancer patients with high expression of EGOT achieved a higher complete pathological response ratio than patients with low expression of EGOT when treated with paclitaxel-containing adjuvant chemotherapy regimens in the HMUCC cohort." (PMID 30999914, 2019). "Regarding paclitaxel sensitivity, breast cancer patients who were treated with paclitaxel and exhibited high expression levels of EGOT demonstrated better OS and RFS than patients with low expression levels of EGOT in the HMUCC cohort." (PMID 30999914, 2019). "Analysis of breast cancer samples from the TCGA data and qRT-PCR studies suggested that lncRNAs, including EGOT, could serve as independent prognostic markers." (PMID 40299341, 2025). "Our present research supports helpful evidence to the anti‐oncogene of EGOT in breast cancer and may extend novel knowledge of therapeutic methods for TNBC." (PMID 32150666, 2020). "This study was conducted to assess the role of EGOT in the progression of breast cancer." (PMID 32150666, 2020). "The aim of this study, therefore, has been to confirm the expression pattern of EGOT in breast cancer cells and adjacent tissues to explore the effects of abnormal expressions in lncRNA EGOT, along with the viability and migration of breast cancer cell lines and the Hh signaling pathway." (PMID 32150666, 2020). "Furthermore, EGOT was upregulated in breast cancer patients who underwent neoadjuvant chemotherapy compared with its expression in patients who did not receive such therapy in the HMUCC cohort." (PMID 30999914, 2019). "Furthermore, examination of CCLE data also revealed that EGOT expression was positively correlated with ITPR1 mRNA expression in human breast cancer cell lines and other cancer cell lines." (PMID 30999914, 2019). "Moreover, dose-dependent inhibition of EGOT expression by E2 was also observed in other ER-positive T47D breast cancer cells." (PMID 30999914, 2019). "Therefore, the role of EGOT in breast cancer progression has been identified as a tumor suppressor." (PMID 32150666, 2020). "To sum up, we constructed a GI-related prognostic risk model comprising six lncRNAs (U62317.4, MAPT-AS1, AC115837.2, EGOT, SEMA3B-AS1, and HOTAIR) in breast cancer." (PMID 35990656, 2022). "The results indicated that MAPT-AS1, EGOT, and SEMA3B-AS1 were downregulated while the expression of HOTAIR was increased in breast cancer cell lines, which were consistent with the predicted results." (PMID 35990656, 2022). "Compared with the normal mammary cells, the qRT-PCR showed that HOTAIR was upregulated while MAPT-AS1, EGOT, and SEMA3B-AS1 were downregulated in breast cancer cells." (PMID 35990656, 2022). "The result was validated using breast cancer specimens in the HMUCC cohort; moreover, EGOT expression was also positively correlated with ITPR1 protein expression in the HMUCC cohort." (PMID 30999914, 2019). "It should be also noted that our ERα-dependent lncRNA set does not contain most of the lncRNAs that were previously studied in breast cancer, such as HOTAIR, CCAT2, UCA1, MALAT1, BCAR4, EGOT, SPRY4-IT1 and others." (PMID 26621851, 2016). "In addition, MAPT-AS1, EGOT, SEMA3B-AS1, and HOTAIR were further verified in normal mammary epithelial cells (HBL100) as well as five human breast cancer cell lines by real-time PCR." (PMID 35990656, 2022). "High EGOT expression correlates with longer disease-free and overall survival in viral infections, blood cancers, glioma, and breast cancers, but not in gastric cancers since high expression correlates with shorter survival times." (PMID 32466143, 2020). "Interestingly, we found that Gli1 was significantly up‐regulated in breast cancer tissues, whereas PTCH1, SMO, Gli1 and HHIP at mRNA and protein levels were all down‐regulated after controlling for EGOT overexpression." (PMID 32150666, 2020).
breast carcinoma (continued). "Consistently, breast cancer tissues with higher EGOT levels showed higher ITPR1 and LC3B levels in the HMUCC cohort, suggesting that the increased expression of EGOT may force a connection with the autophagic pathway via ITPR1." (PMID 30999914, 2019).
colon cancer (3 papers, 2023 to 2025). "Moreover, EGOT was found to potentially impede the proliferation and spread of colon cancer via modulating autophagy, making it a potential therapeutic target and diagnostic marker for colon cancer." (PMID 37588204, 2024). "For example, DNAJC3-AS1, EGOT, and LINC00261 are considered clinical markers of colon cancer and are involved in regulating cell proliferation and invasion." (PMID 37448887, 2023).
renal cell carcinoma (3 papers, 2024 to 2025). "EGOT encodes for a long noncoding RNA that has been reported to inhibit cell migration and proliferation in breast and renal cell carcinoma, but its role in NSCLC is unclear." (PMID 38674080, 2024). "Dysregulated EGOT expression has been observed in various cancers, including head and neck, breast, hepatocellular carcinoma, rectal cancer, gastric cancer, renal cell carcinoma, thyroid cancer, and glioma." (PMID 40299341, 2025).
thyroid cancer (3 papers, 2017 to 2025). "EGOT is a crucial regulator in the most cancers, such as liver and thyroid cancer." (PMID 40699783, 2025).
gastric cancer (2 papers, 2024 to 2025). A primary or metastatic malignant neoplasm involving the stomach. "Similarly, EGOT research in gastric cancer also found that the loss of EGOT led to the down-regulation of Hedgehog signaling pathway, and could inhibit the proliferation function by preventing the G1 phase cycle process of GC cells." (PMID 39411134, 2024).
glioma (2 papers, 2019 to 2025). A benign or malignant brain and spinal cord tumor that arises from glial cells (astrocytes, oligodendrocytes, ependymal cells). "Moreover, the expression level of EGOT varies among different glioma cell lines, with the lowest level in the U251 and U87 cell lines, which are believed to be the most aggressive type." (PMID 31805879, 2019). "This phenomenon might be because the expression of EGOT can arrest the cell cycle in the G0/G1 phase and reduce glioma cell proliferation." (PMID 31805879, 2019).
viral infection (2 papers, 2018 to 2025). "Our analysis revealed correlations between EGOT expression and genes involved in the cell cycle, immune response, and viral infections." (PMID 40299341, 2025).
COVID-19 (1 paper, 2021). A disease caused by infection with severe acute respiratory syndrome coronavirus 2. "The result obtained for the time points and type of IFN treatment reduced expression of EGOT, GABPB1-AS1, IDI2-AS1, LINC00312, LINC00662, MIAT, PVT1, SNHG7; expression of these lncRNA was increased in SARS-CoV-2 infected cells or in the tissue obtained from COVID-19 patients." (PMID 34940755, 2021).
head and neck squamous cell carcinoma (1 paper, 2025). A squamous cell carcinoma that arises from any of the following anatomic sites: lip and oral cavity, nasal cavity, paranasal sinuses, pharynx, larynx, and salivary glands. "Using the UALCAN database, we confirmed significant upregulation of these genes in HPV(+) versus HPV(−) head and neck squamous cell carcinoma patients, underscoring the role of EGOT in HPV infection." (PMID 40299341, 2025).
laryngeal squamous cell carcinoma (1 paper, 2024). A squamous cell carcinoma that arises from the larynx. "Besides, the interaction pairs of HCG22/EGOT-hsa-miR-1275-FAM107A and HCG22/EGOT-hsa-miR-1246-Glycerol-3-phosphate dehydrogenase 1 are likely to have a significant role in laryngeal squamous cell carcinoma." (PMID 38609844, 2024).
rectal cancer (1 paper, 2025). A primary or metastatic malignant neoplasm that affects the rectum. "EGOT expression was elevated in rectal cancer patients and cell lines, correlating with worse survival." (PMID 40299341, 2025).
tumor (10 papers, 2019 to 2025). "We then validated that the overexpression of EGOT repressed the tumor growth of TC cells in nude mice compared with the control plasmid, as demonstrated by the reduced tumor size, tumor volume, and tumor weight." (PMID 38006396, 2023). "SPP1, CRYAB, NNMT and HILPDA were highly expressed in tumour cells (ccRCC1); GSTA2, BHMT and ADSSL1 were highly expressed in tumour cells 1 (ccRCC2); and HIF1A-AS2, DNAH11 and EGOT were highly differentially expressed in tumour cells 2 (ccRCC2)." (PMID 34168986, 2021). "This most likely indicates one glaring insight: the higher the malignancy of the tumor and the larger the Ki67 value, the lower the expression of EGOT (P < 0.0001)." (PMID 32150666, 2020). "For some tumors, such as renal cell carcinoma, EGOT is a tumor suppressor and is likely a potential prognostic biomarker for kidney cancer." (PMID 32150666, 2020). "Interestingly, our findings indicate that the lncRNAs LINP1 and EGOT are released from tumor cells, whereas BREA2 and LINC01503 primarily originate from the exosomes of immune cells." (PMID 40925917, 2025). "We found that EGOT and LINP1 were highly expressed in exosome-free supernatants derived from tumor cells." (PMID 40925917, 2025). "On the other hand, overexpressing LINP1 and EGOT and silencing BREA2 and LINC01503 significantly reduced the sensitivity of tumor cells to T-DM1 and increased their ability to invade and increase their colony formation capacity." (PMID 40925917, 2025).
cancer (7 papers, 2019 to 2025). A tumor composed of atypical neoplastic, often pleomorphic cells that invade other tissues. "In previous studies, lncRNA EGOT has been identified as a potential prognostic biomarker in various cancers." (PMID 40299341, 2025). "Seven related LncRNAs (LINC01871, AP003469.4, Z68871.1, AC245297.3, EGOT, TFAP2A-AS1, SEMA3B-AS1) were reported to be associated with cancer." (PMID 36353118, 2022). "Our data also show that EGOT is positively and negatively transcriptionally regulated by hypoxia and estrogen-related stress, respectively, in human cancer." (PMID 30999914, 2019). "To validate the potential function of EGOT in mediating the paclitaxel response, we then generated stable overexpression and knockdown of EGOT in cancer cell lines." (PMID 30999914, 2019). "We determined that EGOT overexpression significantly increased the sensitivity of cancer cells to paclitaxel." (PMID 30999914, 2019). "Given its significance in the autophagy signaling pathway, EGOT may be act as a promising predictive biomarker for paclitaxel response, and proper regulation of EGOT may be a novel synergistic strategy for enhancing paclitaxel sensitivity in human cancer." (PMID 30999914, 2019). "By fractionated nuclear and cytoplasmic RNA analysis and RNA fluorescence in situ hybridization (RNA-FISH) examination in four cancer cell lines, we found that EGOT is mainly expressed in the nucleus, suggesting that EGOT exerts its regulatory function for ITPR1 at the transcriptional level." (PMID 30999914, 2019). "Conversely, silencing EGOT protected cancer cells from paclitaxel." (PMID 30999914, 2019). "Therefore, EGOT/ITPR1 expression is associated with a favorable prognosis and enhances paclitaxel sensitivity in human cancer." (PMID 30999914, 2019). "Overall, we provide compelling evidence that in response to stress, EGOT activates autophagy via ITPR1, which sensitizes paclitaxel cytotoxicity in human cancer." (PMID 30999914, 2019).
infection (3 papers, 2018 to 2025). The state of being infected such as from the introduction of a foreign agent such as serum, vaccine, antigenic substance or organism. "Increased expression of NEAT1, MALAT1, EGOT, PVT1, MIAT has been also observed in infection with other viruses." (PMID 34940755, 2021). "This repressive role of EGOT resembles what has been described for the lncRNAs NRIR and NRAV, negative regulators of the IFN pathway which are induced by IFN or infection." (PMID 29503633, 2018). "EGOT was also induced in response to very high doses of IFN-α, but at much lower levels compared to what is observed after infection with RNA viruses." (PMID 29503633, 2018).
EGOT also shares sentences with these, for which no sentence is quoted: hepatocellular carcinoma (2 papers); Hepatic fibrosis (1); Hepatitis (1); kidney tumors (1); lung carcinoma (1).